ETS2 (ETS proto-oncogene 2, transcription factor)
Description:
Transcription factor activating transcription. Binds specifically the DNA GGAA/T core motif (Ets-binding site or EBS) in gene promoters and stimulates transcription.
Synonyms: ETS2IT1
Tractability: Antibody: its Gene Ontology location is reachable by antibodies, with high confidence. PROTAC: ubiquitination databases record sites on it.
Safety:
Unwanted effects reported when the protein is acted on. In parentheses: how it was acted on, where the effect was seen, and who reports it.
thrombocytopenia (source: ClinPGx)
Gene: Protein-coding gene on chromosome 21 (38,805,115 to 38,824,956, forward strand). Ensembl gene ENSG00000157557.
Subcellular location: Nucleus
Subcellular location (Human Protein Atlas): Nucleoplasm; Cytosol; Plasma membrane
Pathways (Reactome):
Cellular responses to stimuli: Oncogene Induced Senescence
Gene Ontology:
Molecular function: DNA-binding transcription repressor activity, RNA polymerase II-specific; protein binding; protein domain specific binding; RNA polymerase II cis-regulatory region sequence-specific DNA binding; RNA polymerase II-specific DNA-binding transcription factor binding; sequence-specific double-stranded DNA binding; DNA binding; DNA-binding transcription factor activity; DNA-binding transcription factor activity, RNA polymerase II-specific; nuclear glucocorticoid receptor binding; RNA polymerase II transcription regulatory region sequence-specific DNA binding; sequence-specific DNA binding
Biological process: negative regulation of transcription by RNA polymerase II; positive regulation of transcription by RNA polymerase II; cell differentiation; regulation of transcription by RNA polymerase II; skeletal system development; regulation of DNA-templated transcription
Cellular component: nucleoplasm; nucleus; chromatin
Genetic constraint (gnomAD): Loss-of-function variants: 12 observed, 44.84 expected, observed/expected ratio (o/e) 0.27, 90% interval 0.17 to 0.43. The upper end of that interval is the gene's LOEUF score, 0.43, which puts it in group 1 of 6, group 1 being the genes least tolerant of losing a copy. Missense variants: 357 observed, 542.05 expected, observed/expected ratio (o/e) 0.66, 90% interval 0.6 to 0.72. Synonymous variants: 198 observed, 216.56 expected, observed/expected ratio (o/e) 0.91, 90% interval 0.81 to 1.03.
Homologues: Orthologues: chimpanzee ETS2 (100% identical), macaque ETS2 (99% identical), dog ETS2 (92% identical), rat Ets2 (92% identical), mouse Ets2 (92% identical), pig ETS2 (91% identical), rabbit ETS2 (88% identical), guinea pig ETS2 (87% identical), tropical clawed frog ets2 (69% identical). Paralogues in human: ETS1 (51% identical), ERG (26% identical), GABPA (26% identical), FLI1 (25% identical), ETV1 (22% identical), ETV5 (21% identical), ETV2 (20% identical), ETV4 (20% identical), ETV6 (19% identical), SPDEF (18% identical), ELF2 (17% identical), FEV (16% identical), and 16 more.
Diseases named in the same sentence as ETS2 in open-access papers:
ETS2 is named in the same sentence as 125 diseases in open-access papers, as found by Europe PMC text mining. Sharing a sentence is not in itself a finding about the gene and the disease. The quoted sentences say what the papers report.
breast cancer (37 papers, 2004 to 2025). A primary or metastatic malignant neoplasm involving the breast. "ETS1 has been implicated in various cancers, including lung and breast cancer, where it cooperates with other transcription factors like ETS2 to influence gene expression related to cell invasion and metastasis." (PMID 40938895, 2025). "The survival curves show that in breast cancer, low expression of ETS2 and RCAN1 is associated with a significantly lower probability of survival." (PMID 37107558, 2023). "This group of genes included three transcriptional activators PBX1, SOX4 and ETS2, which have been linked to breast cancer tumorigenesis." (PMID 23301048, 2013). "Similarly, inhibition of MMP9 production in tumour-associated macrophages by a hypomorphic Ets-2 mutation also inhibited tumour development in the PyMT mouse model of breast cancer." (PMID 15164120, 2004). "For example, overexpression of ETS2 is intimately related to tumor progression, invasion, and metastasis in breast cancer, colorectal cancer, and prostate cancer." (PMID 40938895, 2025). "The interaction of SRC‐1 and Ets2 regulates MMP9 target genes expression in Aromatase inhibitors resistance in breast cancer cells." (PMID 38506084, 2024). "ETS2 has been reported to play critical roles throughout all stages of tumorigenesis and was demonstrated to promote angiogenesis in breast cancer." (PMID 38670309, 2024). "SRC‐1 and Ets2 interact to regulate expression of MMP9 target genes in Aromatase inhibitors resistance in breast cancer cells." (PMID 38506084, 2024). "Further research is needed to ascertain the biological conditions that instigate the opposing roles of ETS2 in breast cancer." (PMID 37107558, 2023). "ETS2 promotes telomerase expression, RARG has been linked with tamoxifen resistance in breast cancer patients, and VEZF1 is a regulator of angiogenesis." (PMID 37367050, 2023). "Conversely, transfection of MCF-12A breast cancer cells with ETS2 promotes proliferation, adhesiveness, and invasiveness." (PMID 37107558, 2023). "ETS1 is reported to up-regulate PARP1 in Ewing sarcoma and ovarian cancer, while ETS1 and ETS2 repress BRCA1 in breast cancer." (PMID 36814284, 2023). "The upregulation of ETS2 was found in acute myeloid leukaemia, prostate cancers, renal cell carcinoma and breast cancer, and it shows close correlation with poor prognosis." (PMID 32015217, 2020). "A previous report indicated combined activation of TERT expression by MYC and ETS2 at this location in breast cancer cells." (PMID 28978027, 2017). "Silencing of ETS2 results in a reduction of TERT gene expression leading to increased human breast cancer cell death, while reconstitution with recombinant TERT reverses that effect." (PMID 28184371, 2017). "In mouse mammary tumor models, Ets2 was shown to support tumor growth from an undefined cell population in the tumor stroma." (PMID 23977064, 2013). "Both Ets1 and Ets2 expression are correlated with decreased disease-free survival in breast cancer patients and a dominant negative Ets construct can inhibit the anchorage independent growth of breast cancer cell lines." (PMID 23874775, 2013). "Comparisons with human stromal gene expression demonstrate the mouse Ets2 pathway functions in human breast cancer progression and correlates with worsened patient outcomes." (PMID 23977064, 2013).
breast cancer (continued). "The fibroblast Ets2 transcriptomes were represented in human breast cancer stroma and correlated with patient outcome in independent whole-tumor breast cancer gene expression data sets." (PMID 23977064, 2013). "Previous work from our group has shown Ets2 functions to promote tumor progression and metastasis in at least two compartments of the mammary tumor microenvironment, including tumor macrophages and breast stromal fibroblasts in which Pten was deleted." (PMID 23977064, 2013). "In mouse models of breast cancer, Pea3 and Ets2 have been shown to exert tumor-promoting effects, the former in the epithelium and the latter in the stroma." (PMID 19545444, 2009). "It is of interest to note that a number of the TFs that bind in the exon -2a cluster have indeed been implicated in breast cancer progression, including LEF, ETS-1, ETS-2 and NFAT3." (PMID 19357769, 2009). "Furthermore, it’s worth noting that ETS2 has been reported to be overexpressed in breast carcinomas." (PMID 38486041, 2024). "Furthermore, ETS2 interacts with c-Myc oncogene to maintain hTERT expression in breast cancer, sustaining the replicative potential of the cancer cells." (PMID 37107558, 2023). "Genetic deletion of CSF-1 resulted in reduction of mammary TAMs and in lower incidence of lung metastasis in in vivo mammary tumor mouse models, deletion of ETS2 in macrophages resulted in reduced metastatic tumor burden and its elevated expression has been correlated with human breast cancer." (PMID 31057539, 2019). "Moreover, depletion of Ets2 in TAMs decreased the frequency and size of lung metastases in three different mouse models using breast cancer cells." (PMID 30597969, 2018). "Furthermore, Ets2-expressing TAMs, displayed a gene signature consisting of 133 genes in human breast cancer expression data which retrospectively predicted the overall survival of breast cancer patients in two independent data sets." (PMID 30597969, 2018). "However, we predicted that Ets1 and Ets2 are the potential binding proteins of the Ets site based on their overexpression in breast carcinomas like MCF-7 used in this study and their regulation by PMA through PKC pathway activation." (PMID 25490397, 2014). "Conditional ablation of Ets2 in TAMs results in decreased angiogenesis and reduced growth of mouse mammary tumors, as well as the reduced frequency and size of lung metastases, suggesting that Ets2 serves as the driver for a transcriptional program that promotes angiogenesis of breast tumors." (PMID 24314323, 2013). "Our study, ensuring more efficient recombination of the conditional Ets2 allele, unequivocally demonstrates that Ets2 is not required in mammary tumor cells in the PyMT model employed in both studies." (PMID 23977064, 2013). "In breast cancer cells, ETS2 may inhibit invasive properties." (PMID 37107558, 2023). "Importantly, the Ets2-dependent gene expression signatures from both mouse models were able to distinguish human breast tumor stroma from normal stroma, and correlated with patient outcomes in two whole tumor breast cancer data sets." (PMID 23977064, 2013). "Several transcriptional activators have been identified to regulate hTERT expression in breast cancer cells, including c-MYC, STAT3, NF-κB, ETS2, ERα, Sp1, KLF4, and ZEB1/YAP, among others." (PMID 37612721, 2023). "Pair-wise gene expression correlation analyses revealed that ETS2 and RCAN1 are positively correlated in breast and lung cancers, with a stronger correlation seen in breast cancer." (PMID 37107558, 2023). "In breast cancer cells, MYC binds to an ETS2 site (EtsA) in the TERT gene promoter and increases TERT expression levels." (PMID 29100407, 2017).
breast cancer (continued). "Recent studies have shown that CDK10 is a potential tumor suppressor in breast cancers, and CDK10/Ets2/c-RAF signaling has been demonstrated as an important determinant of breast cancer resistance to endocrine therapy." (PMID 26209438, 2015). "The gene expression in tumor of SRC-1, SRC-2/transcription intermediary factor-2 (TIF-2), SRC-3/amplified in breast cancer 1 (AIB1), ER, HER-1, -2, -3 and HER-4, as well as the transcription factor Ets-2, was measured by real-time RT-PCR." (PMID 22703232, 2012). "Gene expression analyses with GEPIA2 and UALCAN showed that DSCR genes ETS2 and RCAN1 are significantly downregulated in breast and lung cancers, and their expression levels are higher in triple-negative compared to luminal and HER2-positive breast cancers." (PMID 37107558, 2023). "In addition, ETS2 、ERαand Sp1, KLF4, and ZEB1/YAP have also been identified as regulators of hTERT transcription in breast cancer cells." (PMID 37612721, 2023). "Similar to ETS2, RCAN1 expression was downregulated in luminal and HER2-positive breast cancers compared to TNBC, suggesting that it may influence the molecular features of breast cancer subtypes." (PMID 37107558, 2023). "The vast majority of research on ETS2 has focused on tumors such as breast cancer and non-small cell lung cancers." (PMID 36582740, 2022). "It has been proposed that ETS2, a member of the ETS transcription factor family which is highly abundant in mammary tissues, cooperates with MYC in the regulation of TERT promoter activity in breast cancer cells." (PMID 28978027, 2017). "ETS2 is important for driving TERT gene expression and breast cancer cell proliferation." (PMID 28184371, 2017). "Ets-2 and SRC-3/AIB1 have been found to be coexpressed in human breast cancer samples." (PMID 22703232, 2012). "Notably, ETS2 was discovered to be downregulated in various cancers, such as THCA, bladder cancer (BLCA), diffuse large B-cell lymphoma (DLBC), glioblastoma multiforme (GBM), and breast cancer (BRCA), with the most pronounced downregulation observed in THCA." (PMID 40938895, 2025). "Furthermore, ETS2 levels were lower in luminal and HER2-positive breast cancers compared to TNBC, indicating that it may play a role in the molecular profiles that characterize these breast cancer subtypes." (PMID 37107558, 2023). "The UALCAN analyses showed that ETS2 and RCAN1 expressions were not influenced by breast cancer stages." (PMID 37107558, 2023).
prostate carcinoma (18 papers, 2012 to 2025). A carcinoma that arises from epithelial cells of the prostate gland. "TRPM2, ITGB2, and ETS2 are located on chromosome 21 and are associated with breast, ovarian, and prostate cancers." (PMID 38803515, 2024). "We recently reported that Gnetin C, a resveratrol (Res) dimer, demonstrated more potent inhibition of metastasis-associated protein 1/v-ets avian erythroblastosis virus E26 oncogene homolog 2 (MTA1/ETS2) axis in prostate cancer cell lines than other stilbenes." (PMID 33255879, 2020). "Our model identified several transcription factors associated with prostate cancer metastasis, such as ETS2, HOXC4, STAT3, STAT5B, SOX4 and ZEB2." (PMID 23782521, 2013). "They found that Ets2-targeting TFO can act as a selective transcriptional repressor of Ets2 transcription in human prostate cancer cells, suggesting that the triplex formation was the functional mechanism of the anti-transcriptional activity of the Ets2-TFO." (PMID 36618947, 2022). "We recently reported that Gnetin C acts through MTA1/ETS2-mediated mechanisms in prostate cancer and shows significant MTA1-mediated inhibitory effects on cell viability, colony formation, and migration while inducing cell cycle arrest and cell death." (PMID 33255879, 2020). "We demonstrated that Gnetin C inhibited MTA1-mediated cell viability, clonogenic survival, migration and induced MTA1-mediated apoptosis more potently than Res and Pter in prostate cancer cells specifically acting through MTA1/ETS2 pathway." (PMID 33255879, 2020). "ETV-4 has been reported to be associated with ETS-2 and ERG, and formed a complex integrated transcriptional network in PC3 cell nuclear extracts and prostate cancer tissues." (PMID 29915163, 2018). "Studies with other ETS proteins, such as ETS-2, have shown that a similar down-regulation of cyclin D1 occurs upon ETS-2 reduction in prostate cancer cells, resulting in growth inhibition." (PMID 29050229, 2017). "This study revealed the specific role of Ets-2 in promoting growth and survival of prostate cancer cells." (PMID 24069250, 2013). "Studies in colon cancer mouse models and more recently in human prostate cancer samples provide evidence that Ets2 can also function as a tumor suppressor gene." (PMID 23977064, 2013). "Target genes of differentially methylated enhancers were notably enriched in developmental pathways, various gene sets of known transcription factor (TF) targets (ETS2 proto-oncogene, FOXO4 tumour suppressor), and in prostate cancer-associated pathways (Dataset EV14)." (PMID 41057544, 2025). "The finding in this study could provide novel therapeutic targets and diagnostics for future ESCC therapy, as direct inhibition of Ets2 transcription by triplex forming oligonucleotides resulted in growth inhibition and induction of apoptosis in human prostate cancer cells." (PMID 27556183, 2016). "ETS2, belonging to the ETS family which could regulate telomerase activity, was highly expressed in prostate cancers." (PMID 31480180, 2020). "For example, Ets2 amplification has also been demonstrated in patients with acute nonlymphoblastic leukaemia, and Ets2 is expressed at elevated levels in breast, ocular neoplasm, cervical and prostate cancer." (PMID 27556183, 2016).
colorectal cancer (14 papers, 2011 to 2025). A primary or metastatic malignant neoplasm that affects the colon or rectum. "Dysregulation of ETS2 expression can exacerbate intestinal inflammation, promote fibrosis, and increase the risk of colorectal cancer in IBD patients." (PMID 40922284, 2025). "Beyond fibrosis, ETS2 has also been implicated in the increased risk of colorectal cancer (CRC) among IBD patients." (PMID 40922284, 2025). "Genetic variants of ETS2 may contribute to disease susceptibility, and its dysregulation is associated with the progression of fibrosis and the increased risk of colorectal cancer in IBD patients." (PMID 40922284, 2025). "RNA-binding protein CELF1 contributes to migration, invasion, and chemotherapy resistance by targeting ETS2 in colorectal cancer and could be a potential diagnostic and prognostic marker." (PMID 32873282, 2020). "ETS2 was shown to be associated with metastasis of colorectal carcinoma." (PMID 29228695, 2017). "This review explores the molecular characteristics of ETS2, its involvement in immune dysregulation, and its contribution to IBD-associated complications, including fibrosis and colorectal cancer." (PMID 40922284, 2025). "It is known that ETS2, a proto-oncogene belonging to the erythroblastosis virus E26 family, is overexpressed in a wide range of human cancers, which include colorectal cancer." (PMID 38054820, 2023). "Previous study have demonstrated that RNA-binding protein CELF1 targeted ETS2 in colorectal cancer, contributing to tumor cell migration, invasion and promotion of chemoresistance." (PMID 36991138, 2023). "By targeting ETS2 in colorectal cancer, it enhanced cell migration, invasion, as well as chemoresistance." (PMID 34628367, 2021). "A transcription regulatory complex (TRC) that includes Ets1, Ets2, PEA3 and β-catenin/T-cell factors regulates osteopontin (OPN) that is implicated in colorectal cancer (CRC) dissemination." (PMID 21343932, 2011). "Furthermore, CELF1 enhances cell migration, invasion, and chemoresistance in colorectal cancer by targeting ETS2." (PMID 40781108, 2025). "Additionally, Ets2 has been identified as a Wnt target in colorectal cancer cells and intestinal stem cells." (PMID 27556183, 2016). "Besides, ETS1 could regulate cell viability via interfering glycolysis in pancreatic cancer; increased expression of ETS2 promotes drug resistance in colorectal cancer." (PMID 33585247, 2020). "In colorectal cancer, MECOM preferentially activates the proto-oncogene ETS2 by binding to its distal super-enhancer." (PMID 40664642, 2025). "Here, we report that a candidate oncogene ETS2 was activated by a distal SE in inflammatory bowel disease (IBD) and colorectal cancer (CRC)." (PMID 36609474, 2023). "The top 5 types of cancer containing ETS2 alteration were UCEC, colorectal cancer, BLCA, BRAC, and bone cancer." (PMID 36760475, 2023).